DPP4 (dipeptidyl peptidase 4)
Diseases named in the same sentence as DPP4 in open-access papers (continued):
Sharing a sentence is not in itself a finding about the gene and the disease.
diabetes (continued). "The results of this study confirmed that DPP-4 inhibitors could effectively improve HbA1C in elderly patients with type 2 diabetes mellitus." (PMID 32368255, 2020). "Therefore, DPP-4 inhibitors have hypoglycemic effects by inhibiting the degradation of GLP-1 in patients with type 2 diabetes mellitus." (PMID 32948146, 2020). "DPP‐4 inhibitors, such as sitagliptin, alogliptin, vildagliptin, saxagliptin and linagliptin, which selectively inhibit the catalytic activity of cell‐associated and circulating soluble DPP‐4, are widely used drugs against diabetes." (PMID 32713161, 2020). "DPP-4 inhibitors like the orally administered sitagliptin are widely used in the therapy of diabetes mellitus as they prolong the action of incretin hormones, including GLP-1 and glucose-dependent insulinotropic polypeptide, by interfering with their degradation in vivo." (PMID 32566677, 2020). "Based on our previous report showing the potential of EMT and metastasis-promoting effects of DPP-4 inhibitors, which are widely prescribed drugs to treat diabetes, we tested whether DPP-4 inhibitors could induce chemoresistance in breast cancer cells." (PMID 31991851, 2020). "In addition, the diabetes treatments associated with GLP-1 agonism and DPP-4 inhibition have also shown neuroprotective effects in preclinical studies and promising results in reducing major cardiovascular events specifically in type 2 diabetes patients." (PMID 32854248, 2020). "Inhibitors of dipeptidyl peptidase-4 (DPP-4) have emerged in the treatment paradigm of diabetes." (PMID 33150239, 2020). "Indeed, it is known that DPP-4 inhibitors are less effective for treating diabetes in obese patients." (PMID 31969650, 2020). "The DPP4 inhibitors vildagliptin and sitagliptin improved cardiac function after myocardial infarction through activation of autophagy in the rodent models of diabetes." (PMID 32340263, 2020). "DPP4 inhibitors are therapeutic drugs for diabetes with anti-inflammatory effects." (PMID 32104696, 2020). "However, more clinical studies are needed to confirm the effect of DPP-4 inhibitors on weight improvement in elderly patients with diabetes mellitus." (PMID 32368255, 2020). "FTIR, mass spectrometry and in silico studies reveal the presence of phytochemicals in garlic extract that are probably responsible for DPP-4 inhibition and provide a new mechanism of action of garlic extract to be used for treatment and management of diabetes mellitus." (PMID 32075130, 2020). "After DPP-4 inhibitors were used in elderly patients with type 2 diabetes mellitus, the elevated glycosylated hemoglobin could be controlled with improved safety of liver and kidney, and might have the effect of weight loss." (PMID 32368255, 2020). "Therefore, future studies should be performed to elucidate the function of DPP4 in the pathogenesis of bone metabolism in diabetes mellitus." (PMID 33312197, 2020). "Accordingly, DPP4 inhibitors have clinical benefits in patients with diabetes mellitus." (PMID 32104696, 2020). "More and more people realize that DPP-4 inhibitors may play a huge role in fighting COVID-19 combined with diabetes." (PMID 33031311, 2020). "Preclinical data have suggested that dipeptidyl peptidase-4 (DPP-4) inhibitors, a glucose-lowering treatment for diabetes, may promote metastatic progression of preexisting cancer via activation of Nrf2 in the cancer cells." (PMID 33158045, 2020). "Moreover, DPP-4 is overexpressed in a number of metabolic diseases (including diabetes, obesity, cardiovascular disease) or cancer." (PMID 33256016, 2020). "Our results suggest that EGCG and DPP4 may interact, which could provide a theoretical basis for improving diabetes-related metabolic abnormalities by tea polyphenols." (PMID 32104696, 2020). "DPP-4 inhibitors are registered for treatment of diabetes mellitus type 2." (PMID 31434198, 2019).
diabetes (continued). "Dipeptidyl peptidase-4 inhibitors (DPP-4i) are emerging glucose-lowering agents through interacting with DPP-4 substrate, impact of which on systemic inflammation in type 2 diabetes mellitus (T2DM) remains unknown." (PMID 31208420, 2019). "We have developed a selective, non-invasive, 13C-assay for DPP4 that could have broad translational applications in diabetes and gastrointestinal disease." (PMID 30894647, 2019). "Our study proposed HCD as a new DPP-4 inhibitor and further validated tits hypoglycemic efficacy in diabetic mice, which could be a new alternative hope for treating diabetes." (PMID 30691220, 2019). "The DPP-4 inhibitors, such as Sitagliptin, Vildagliptin, Linagliptin, Teneligliptin, Anagliptin, Trelagliptin, and Omarigliptin are already in use for clinical treatment of diabetes." (PMID 30889182, 2019). "DPP-4i are a new class of anti-diabetes drugs that prevent the degradation of glucose-dependent insulinotropic polypeptide and glucagon-like peptide 1 by inhibiting dipeptidyl peptidase-IV (DPP-4)." (PMID 31297116, 2019). "Screening DPP-4 inhibitors for treating diabetes is a recently developing field (since 2006), when a study reported that DPP-4 might regulate insulin sensitivity via degradation of GLP-1." (PMID 30691220, 2019). "One confounding factor should be the anti-diabetes therapies like metformin, sulfonylureas, or DPP-4 inhibitor, which may alter the circulating miRNA expression pattern of the diabetes patients." (PMID 31383887, 2019). "Since these incretins can enhance insulin secretion in a glucose-dependent fashion, DPP4 could be considered strictly related to the pathophysiology of type 2 diabetes mellitus." (PMID 30886868, 2019). "DPP4 inhibitors are also widely used diabetes drugs worldwide." (PMID 30824564, 2019). "In the present study, patients with diabetes and DPP-4 inhibitors had a lower incidence rate of AR." (PMID 31013793, 2019). "Currently, there are various drugs used to treat diabetes mellitus, including insulin secretagogues, insulin sensitizer, α-glucosidase inhibitor, insulin, or insulin analogues, dipeptidyl peptidase-4 (DPP-4) inhibitor, glucagon-like peptide-1 (GLP-1) analogues, and other oral antidiabetic drugs." (PMID 31950036, 2019). "One possible explanation of our finding that Gal-4 is associated with both incident and prevalent diabetes is that increased expression of Gal-4 leads to increased activity of DPP-4 and thus reduced activity of GLP-1 and increased risk of diabetes and cardiovascular complications." (PMID 30670722, 2019). "Long-term outcomes trials with several different DPP-4 inhibitors have been performed, and their results are worth examining in order to understand both the mechanisms of action as well as the appropriate place of this class of drugs in diabetes care." (PMID 29310647, 2018). "Our findings further suggest a potential novel avenue for host-directed therapy as DPP4 inhibitors used in the treatment of diabetes could be refurbished for patients with TB and MDR-TB." (PMID 30026741, 2018). "For the meta-analysis comparing the efficacy and safety between SGLT2 inhibitor plus DPP4 inhibitor (SGLT2i/DPP4i) and placebo plus DPP4 inhibitor (PCB/DPP4i) in patients with type 2 diabetes mellitus (T2DM), we selected randomized controlled trials from electronic databases by predefined criteria." (PMID 29535389, 2018). "However, in our study, the risk of hypoglycemia increased when SGLT2 inhibitors were sequentially added to pre-existing DPP4 inhibitors, which was probably due to a study that permitted insulin and/or sulfonylureas as background anti-diabetes therapy." (PMID 29535389, 2018). "This provides new knowledge on the mechanisms at the basis of the beneficial effects of DPP-4 inhibitors in the T2D brain that could be exploited to design preventive therapies to treat cognitive decline in diabetes." (PMID 29471869, 2018).
diabetes (continued). "Currently, safer glucose-dependent glycaemic control with DPP-4 inhibitors may be the best choice of treatment in those with diabetes with impaired kidney function." (PMID 29417185, 2018). "DPP4 inhibitors (Sitagliptin, Vildagliptin, Alogliptin, and Saxagliptin) have become mainstay oral hypoglycaemic therapies in type 2 diabetes mellitus based on their capacity to prevent breakdown and prolong the activity of the incretin glucagon-like peptide 1 (GLP-1)." (PMID 29040423, 2018). "We investigated the impact of the DPP-4 inhibitor linagliptin on markers of endothelial function and postprandial lipid excursions in subjects with established coronary artery disease and early diabetes treated either with diet alone or metformin monotherapy." (PMID 29773079, 2018). "Stratification according to pre-study diabetes treatment regimens, amongst which were switches from another sulfonylurea or a dipeptidyl peptidase-4 inhibitor (DPP-4i), revealed significant HbA1c improvements with gliclazide MR in all four strata examined (P < 0.001)." (PMID 29651307, 2018). "DPP4 is the target for a class of enzyme inhibitors used in the treatment of diabetes, and the results from this study suggest that these drugs could be repurposed as an adjunct immunotherapy of patients with TB and MDR-TB." (PMID 30026741, 2018). "Indeed, the most recent addition to the body of evidence is a population-based, retrospective cohort study of 255 691 South Korean patients with type 2 diabetes mellitus newly prescribed either DPP-4 inhibitors or sulfonylureas." (PMID 29040423, 2018). "Dipeptidyl peptidase 4 (DPP-4) inhibitors are used for the treatment of type-2 diabetes mellitus." (PMID 29148282, 2018). "Moreover, it illustrated that SG can act via other mechanisms than its DPP4 inhibitory effect to improve I/R and diabetes." (PMID 30072896, 2018). "DPP-4 inhibitors have become standard drugs to improve hemoglobin A1c (HbA1c) levels in patients with diabetes, though improvement of cardiovascular outcomes by adding DPP-4 inhibitors to usual care in diabetic patients with established cardiovascular diseases has not yet been shown." (PMID 29435776, 2018). "On top of their antioxidative effect, flavonoids may act on biological targets involved in type 2 diabetes mellitus such as α-glycosidase and DPP-4." (PMID 29318154, 2017). "In addition, DPP-4 inhibitor treatment had a neutral effect on hypoglycemia, an important barrier in diabetes treatment." (PMID 28182722, 2017). "DPP-4 inhibitors did not increase cardiovascular risk compared with glimepiride regardless of history of CVDs, diabetes duration, and treatment duration." (PMID 28640111, 2017). "Sitagliptin, a DPP-4 inhibitor, is a clinic drug for type 2 diabetes mellitus and could potentially be a treatment for TBI also." (PMID 28846606, 2017). "The association between dipeptidyl peptidase-4 inhibitors (DPP-4is), a class of anti-diabetes, and bone fracture in patients with type 2 diabetes mellitus (T2DM) is unknown." (PMID 29206832, 2017). "The European Diabetes Association and the American Diabetes Association recommend that metformin is prescribed as a first-line drug regardless of body weight, and DPP-4 inhibitors are increasingly being used as second-line treatment as add-on to metformin." (PMID 29017497, 2017). "Since a reduced EPC number is a biomarker and, perhaps, a pathogenetic factor of vascular disease, DPP-4 inhibition by vildagliptin may represent an attractive strategy to treat diabetes, beyond glucose control." (PMID 28231835, 2017). "Although DPP-4 inhibitors are not the drug of first choice for type 2 diabetes mellitus by the guidelines of American Diabetes Association." (PMID 29213240, 2017). "Also, they were less likely to be prescribed combinations of oral blood glucose lowering drugs, dipeptidyl peptidase-4, and exenatide/liraglutide for non-insulin-dependent diabetes mellitus." (PMID 29169334, 2017).
diabetes (continued). "In the sub-analysis by duration of diabetes diagnosis, both groups (<10 years and ≥10 years) showed a significant decrease in all-cause mortality associated with SGLT2 inhibitor use compared with placebo and DPP4 inhibitor use." (PMID 28542373, 2017). "Furthermore, this formulation effectively controlled blood glucose and significantly decreased the body weight of mice, suggesting that MSN-HCD exerts natural DPP4 inhibitor as a potential clinical drug for the treatment of diabetes." (PMID 28498352, 2017). "The LCK participants experienced larger reductions in diabetes-related medication use; of participants who took sulfonylureas or dipeptidyl peptidase-4 inhibitors at baseline, 6/10 in the LCK group discontinued these medications compared with 0/6 in the MCCR group (p = .005)." (PMID 29269731, 2017). "Accordingly, DPP-4 inhibitors have become one of the first-line treatments for diabetes." (PMID 28771625, 2017). "Although diabetes significantly accelerates human premature aging such as brain aging or vascular aging, it is unknown whether DPP-4 inhibition can slow the progression of human premature aging." (PMID 29195509, 2017). "Currently ongoing trials do not specifically focus on early diabetes as a target of intervention and we therefore believe that our study will contribute to a better understanding of the cardiovascular effects of dipeptidylpeptidase-4 (DPP-4) inhibitors in early diabetes." (PMID 27733180, 2016). "Translational research suggests that dipeptidyl peptidase-4 (DPP-4) inhibitors, which are drugs for type 2 diabetes mellitus (T2DM), may prevent cardiovascular disease to a greater extent than other T2DM drugs." (PMID 27351380, 2016). "Indeed, DPP4 activity is increased in proinflammatory states including obesity, diabetes mellitus, and atherosclerosis." (PMID 27654253, 2016). "Furthermore, DPP-4 inhibitors not only have benefits for patients who have recently developed diabetes but also in patients with long-standing diabetes." (PMID 26877767, 2016). "DPP-4 inhibition by DPP-4i was shown to reduce kidney injury in rat models of diabetes." (PMID 28119930, 2016). "In 2012, dipeptidyl peptidase-4 inhibitors were added to the second line of diabetes treatment." (PMID 27843494, 2016). "Importantly, human diabetes patients are characterized by elevation in DPP4 in the plasma and urine." (PMID 27213360, 2016). "In regards to obesity, diabetes, and metabolic syndrome, there has been speculation that dipeptidyl peptidase-4 (DDP-4) and chitinase-3 like protein 1 (CH3L1) activate PAR2." (PMID 27006943, 2016). "Oral antihyperglycemic agents (AHAs), including biguanides, thiazolidinediones (TZDs), alpha-glucosidase inhibitors, meglitinides, dipeptidyl peptidase 4 (DPP-4) inhibitors, and sulfonylureas (SUs), can be used either individually or in combination to treat diabetes." (PMID 26786291, 2016). "Attention then was driven to the expression of DPP4 in injured skin since data obtained in control and diabetic mice reveal that high expression of the enzyme correlates with persistence of an unresolved wound in diabetes." (PMID 26136686, 2015). "This study focused on the effects of a DPP-4 inhibitor on urinary AGT in patients with diabetes." (PMID 26380312, 2015). "Dipeptidyl peptidase 4 (DPP4) is expressed in various tissues, including the skin, and DPP4 inhibitors, that are currently used for the treatment of diabetes, may be effective also for complications of diabetes that affect the skin." (PMID 26136686, 2015). "Recent approaches in drug discovery have contributed to the development of new class of therapeutics like Incretin mimetics, Amylin analogues, GIP analogs, Peroxisome proliferator activated receptors, and dipeptidyl peptidase-4 inhibitor as targets for potential drugs in diabetes treatment." (PMID 26273667, 2015).
diabetes (continued). "In the SAVOR-TIMI 53 trial, which was originally performed to assess the cardiovascular safety of saxagliptin, Leibowitz and colleagues recently reported that DPP4 inhibition may attenuate the progression of diabetes." (PMID 26284071, 2015). "The findings of increased concentrations and activity of DPP4 in patients with diabetes may justify, at least partially, the status of incretin deficiency/resistance related to T2DM." (PMID 26146634, 2015). "The relatively weak clinical benefit of vildagliptin in patients with a long history of diabetes could be partly ascribed to DPP-4 induction evoked by AGEs." (PMID 25582643, 2015). "Although some authors claim that DPP4 inhibitors are only beneficial in early stages of diabetes, this could be rebutted by the work of Kumar and Gupta." (PMID 26284071, 2015). "Because GLP-1 is rapidly inactivated by the enzymatic cleavage of dipeptidyl peptidase-4 (DPP4) long-acting GLP-1 analogues, for example, exenatide and DPP4 inhibitors, for example, liraglutide, have been developed as therapeutics for type 2 diabetes mellitus (T2DM)." (PMID 26788106, 2015). "In addition to lowering blood glucose in patients with type 2 diabetes mellitus, dipeptidyl peptidase 4 (DPP4) inhibitors have been shown to be antifibrotic." (PMID 26509887, 2015). "It is interesting that duration of diabetes does not seem to impair response, suggesting that the ability of DPP-4 inhibitors to augment meal associated insulin secretion does not decline with time of having diabetes." (PMID 25180036, 2014). "Of the existing anti-diabetes treatments licensed for such use in the EU, sufficient data was available to compare dapagliflozin with 2 other classes of agent in the current meta-analysis: DPP-4 inhibitors and GLP-1 analogues." (PMID 25006351, 2014). "Here, we studied whether combining a short-course low-dose anti-CD3 regimen with MK626 (a novel DPP-4 inhibitor) improved diabetes reversal in new-onset diabetic NOD mice." (PMID 25268801, 2014). "DPP4 inhibitors are currently being used clinically in patients with diabetes mellitus." (PMID 26344893, 2014). "Diabetes mellitus should be managed by initiation of medical therapy with metformin and staged treatment intensification with a dipeptidyl peptidase-4 inhibitor, with a switch to a GLP-1 receptor agonist and initiation of insulin, as required, to achieve and maintain glycemic control." (PMID 23564338, 2014). "After 24 weeks of therapy, both agents yielded comparable effects concerning glucose control, as shown by similar HbA1c levels, evidencing that DPP-4 inhibitors can be used later in the course of the disease, still retaining effectiveness in patients with long-standing diabetes." (PMID 25285158, 2014). "Usual diabetes treatment received concomitantly by the participants was diet only (n = 9) or diet plus oral agents (metformin, n = 48; sulfonylurea, n = 43; dipeptidyl peptidase-4 inhibitors, n = 11; glucagon-like peptide-1 agonist, n = 1; acarbose, n = 4; metformin + pioglitazone, n = 1)." (PMID 24891873, 2014). "We developed a therapeutic vaccine against DPP4 for diabetes mellitus treatment." (PMID 26344893, 2014). "The blockade by linagliptin of positive feedback loop between AGE-RAGE axis and DPP-4 might be a novel therapeutic target for vascular injury in diabetes." (PMID 23984879, 2013). "In contrast, recent studies showed that a DPP-4 inhibitor may reduce cardiovascular events in patients with diabetes." (PMID 23298374, 2013). "Among others, DPP4, PEDF as well as MCP-1, decorin and PAI-1 are described to be associated with conditions of obesity, insulin resistance and diabetes." (PMID 23637948, 2013). "Despite the beneficial effect of DPP4i on glucose levels, the high number of substrates of the DPP-4 raise the question whether one substrate (or more) would have negative effects to undermine the beneficial effects of glucose lowering in diabetes patients." (PMID 23537430, 2013).